FGFR2 (fibroblast growth factor receptor 2)
Diseases named in the same sentence as FGFR2 in open-access papers (continued):
Sharing a sentence is not in itself a finding about the gene and the disease.
cancer (continued). "In addition, FGFR2 amplification, present in less than 5% of BC cases, can make cancer cells more resistant to FGFR inhibitors, as seen in pre-clinical models." (PMID 32188012, 2020). "Our findings highlight an improved FGFR2‐targeting cyclic peptide for cancer therapy." (PMID 34766128, 2020). "The signaling pathways we identified in ND MSCs were replaced by MET, WNT, and FGFR2 signal transduction, which may play a role in promoting inflammation, cancer, and aging." (PMID 33361524, 2020). "In this cross-sectional study, an estimated 76.1% of patients with advanced cancer expressing FGFR2 or FGFR3 alterations could be eligible for off-label treatment with erdafitinib." (PMID 31755953, 2019). "We estimated that, of 17 019 patients with advanced cancer expressing FGFR2 or FGFR3 alterations, 12 955 (76.1%) could be eligible for off-label treatment with erdafitinib." (PMID 31755953, 2019). "In cancer, FGFR2 isoform dysregulation has been widely observed." (PMID 31881796, 2019). "Therefore, caution should be taken when considering the use of MEK/ERK pathway inhibitors in cancer patients with FGFR2 expression." (PMID 31146385, 2019). "Moreover, through suppressing FGFR2, the lapatinib resistance can be reversed and the phenotype of cancer-initiating cell can be inhibited by miR-494 in HER2-positive gastric cancer." (PMID 31076630, 2019). "Although one might expect that growth factor receptors to be overexpressed in cancer, several studies have reported that FGFR2 mRNA expression was downregulated in cancer, which is also consistent to our results." (PMID 30837551, 2019). "Twenty-nine patients (18 women, 11 men, median age 58.7 years, 100% Caucasian), with iCCA and FGFR2 gene fusion, whose cancer was unresectable, were enrolled and treated with derazantinib at eight sites in the United States and Italy between August 2014 and October 2017." (PMID 30420614, 2019). "It is reported that an FGFR2 copy number gain is detected in 9% of whole cancers." (PMID 29987267, 2018). "Notably, FGFR2 amplification mainly occurs in genomically stable cancers or cancers with chromosomal instability." (PMID 29573334, 2018). "FGFR2 mRNA were over-expressed in cancers when compared to normal lungs." (PMID 29137669, 2017). "FGFR2 promises potential as biomarker and therapeutic target in other cancer subtypes." (PMID 27650542, 2016). "However, there are only a few cancer cell lines harboring point mutations in the FGFR KD with just two mutations being represented, FGFR3 K650E and FGFR2 N550K." (PMID 26992226, 2016). "FGFR2 expression is correlated with progression and poor prognosis in diverse cancers including GC." (PMID 27107424, 2016). "Furthermore, it was reported that shRNA-targeting FGFR2 in CRC cell lines inhibited cancer cell growth, migration, and invasion." (PMID 26569228, 2015). "FGFR2 positive tumor fibroblasts may provide cancer cells with a suitable microenvironment to promote cancer development and progression." (PMID 25884729, 2015). "Among fellow RTKs, EPHA1, EPHA2, FGFR2, PDGFRß, Ret, and VEGFR2 have often been linked to cancer." (PMID 26073592, 2015). "Thus, constitutive FGFR-2 signaling due to FGFR-2 overexpression can lead to protection from apoptosis which is one of the hallmarks of cancer." (PMID 26465941, 2015). "Since thyroid follicular cells involved in neoplastic transformation are essentially derived from epithelial lineage, we assumed that our KGFR-specific SC-101 mAb could be suitable to highlight FGFR2 modulation in this cancer." (PMID 24899248, 2014). "For AZD4547, the 20,000-fold difference in sensitivity to FGFR inhibitors suggests that FGF signaling is a critical driver to CDH1-initiated gastric cellular proliferation and this TKI represents a potential targeted therapy in diffuse subtype cancers harboring FGFR2 amplifications." (PMID 25315765, 2014).
cancer (continued). "As Clims are direct regulators of Fgfr2 in the mammary gland, the reduced tumorigenicity observed in DN-Clim/PyMT mice could in part be explained by Clim-mediated regulation of Fgfr2 in cancer stem-like cells." (PMID 25079073, 2014). "In addition, treatment of cancer cell lines with FGFR2-specific small molecule inhibitors or shRNAs leads to potent growth inhibition suggesting a functional role for FGFR2 amplification in the diffuse subtype." (PMID 25315765, 2014). "Moreover, previous studies suggested a protective role of FGFR-2 against cancer progression in transformed thyroid carcinoma cells." (PMID 23977259, 2013). "There are many published reports concerning the expression of FGFR2 in various cancers." (PMID 22701813, 2012). "The nuclear signalling by FGFR2 may, therefore, contribute to a protective mechanism against cancer." (PMID 21418638, 2011). "Deregulation of the FGFR2 gene has been identified in a number of cancer sites." (PMID 19500394, 2009). "This hypothesis was highlighted primarily by the identification of risk variants at the FGFR2 and MAP3K1 loci – two genes known to be somatically altered in human cancer and whose products are involved in signal transduction among other processes." (PMID 19094230, 2008). "Next, we examined whether strong expression of FGFR2 in cancer cells correlated with patient prognosis." (PMID 18594526, 2008). "Similarly, FGFR2 product was also much less in cancer tissues (P = 0.0078), as was FGFR1 (P = 0.002)." (PMID 1380281, 1992). "Cavazzoni and colleagues also reported in cancers of unknown primary with FGFR2 amplification that the combination of infigratinib and trametinib was synergistic and reduced the activity of both the AKT/mTOR/p70S6K and the MAPK pathway beyond the effects of the monotherapies." (PMID 40415599, 2025). "Through unbiased phenotypic screening using cancer growth inhibition as a functional readout, we selected 2 biparatopic antibody candidates that achieved highest efficacy in vitro and confirmed their therapeutic activities in FGFR2 fusion ICC xenograft models in vivo." (PMID 40014401, 2025). "Apparently, FGFR2 cancer signalling might be context dependent." (PMID 38473753, 2024). "Notably, large-scale mapping of cancer dependencies showed that FGFR2-fusion+ ICC cells have significantly enriched dependency on SLC2A1 (encoding GLUT1, the high-affinity glucose transporter) relative to other cancer cell lines, consistent with a particularly high demand for glucose at baseline." (PMID 38714664, 2024). "In addition, they found FGFR2 amplification occurred in poorly cohesive carcinomas." (PMID 36416959, 2023). "Small-molecule FGFR2 inhibitors may temporarily control such E-cadherin-deficient cancers due to nonselective FGFR2c cross-inhibition; however, such treatments also select for EMT-driven drug resistance." (PMID 34007277, 2021). "In addition, CHOL and UCEC had high FGFR2 expression, and SKCM had low FGFR2 expression, but in these cancer types, there was no survival association shown between FGFR2 expression and patient prognosis." (PMID 33968743, 2021). "Genetic alterations in FGFR2, including gene amplification, mutations or rearrangements may dysregulate the FGF signaling pathway, influence the development and progression of various cancers by activating the downstream PI3K–AKT and MAPK–ERK pathways." (PMID 34551773, 2021). "Besides this approval, other therapeutic options could be considered, since it was demonstrated that the inhibition of heat-shock protein 90 (HSP90) is an alternative to direct FGFR-kinase inhibition in FGFR2-fusion-driven cancers." (PMID 32781527, 2020).
cancer (continued). "We propose that lack of this feedback loop could give cancer cells an advantage and, indeed, variants of FGFR2 lacking the feedback loop have been identified in several human cancers." (PMID 31146385, 2019). "Therefore, we believe that regorafenib might be effective in patients with FGFR2‐amplified cancers and might be incorporated into treatment against this type of cancer." (PMID 29573334, 2018). "Interestingly, the targetable genes (by administering e.g. cobimetinib, trastuzumab, and ponatinib, respectively, against) MET, HER2, and FGFR2 also displayed the highest difference with a fold change of the mean expressions over 2 when comparing gastric normal and cancer samples." (PMID 27384994, 2016). "In addition, our results targeting FGFR2 suggest that there are specific targets that may be used to successfully eliminate TICs in human cancers." (PMID 23300950, 2013). "Besides these mutations we have also identified several mutated cancer drug targets or genes that are associated with treatment outcome, including BRAF, KRAS, FGFR2 and MTOR, which might help to choose optimal drug combinations." (PMID 21203531, 2010). "Explanation of the lack of strong cancer predisposition, despite the oncogenic nature of the FGFR2 mutations, may lie in the different signalling relationship that a mutant cell has with its neighbours when the mutation is present constitutionally, compared to occurrence as a somatic change." (PMID 42082645, 2026). "The most frequently detected gene fusions using the automated RNA workflow involved ERG, FGFR2, and ALK, consistent with the prevalence reported for similar pan-cancer cohorts." (PMID 39674366, 2025). "A total of 1,501 distinct fusions in at least one of the nine driver genes assessed (ALK, RET, ROS1, NTRK1/2/3, FGFR2, FGFR3, and NRG1) were detected in 1,497 patients for a combined prevalence of 2.2% across the pan-cancer cohort." (PMID 41091579, 2025). "Current studies rely heavily on analogies from other FGFR-driven cancers, with limited GIST-specific data on FGFR2-mediated HRR or NHEJ." (PMID 41150770, 2025). "Peptides comprising PRM-containing C-terminal tail regions of EGFR, FGFR2 and HER2 were used as bait to affinity purify bound proteins from different cancer cell line lysates." (PMID 39165974, 2024). "The binding of TRPA1 and FGFR2 increases the activation of MAPK/ERK and PLC-γ1 pathways, leading to the proliferation and invasion of cancer cells." (PMID 39408656, 2024). "Both immune and mesangial cells interacted with cancer cells of the EMT program via the FGFR2 receptor of the FGF family, with evidence indicating the pivotal role of FGFR2 in mediation of EMT and cancer cell angiogenesis." (PMID 38944814, 2024). "We expand on this early work here by analysis of the interactome for a PRM from each of the RTKs; EGFR, FGFR2 and HER2, in cell lines derived from four cancers that together represent a diverse range of histological subtypes." (PMID 39165974, 2024). "All identified cancer cell lines express SHP2 and certain diffuse gastric cancer (DGC) cell lines with MET or fibroblast growth factor receptor 2 (FGFR2) gene amplification exhibit preferential tyrosine phosphorylation." (PMID 38504984, 2024). "For example, the amplification of FGF receptor 2 (FGFR2), which is less frequent than the amplification of FGF receptor 1 (FGFR1) across cancer types, is often reported in patients with gastric-esophageal junction adenocarcinoma." (PMID 39691707, 2024). "Fibroblast growth factor receptor 2 (FGFR2) belongs to the family of tyrosine kinase receptors known as FGFR, which participate in various signalling pathways that impact cancer-related processes such as cell proliferation, apoptosis, and differentiation." (PMID 39390525, 2024).
cancer (continued). "The inhibitors pemigatinib, futibatinib, and RLY-4008 showed activity in multiple disease types and FGFR alterations (with RLY-4008 being FGFR2-specific), though additional follow-up is needed to determine the utility of targeting FGFR pan-cancer." (PMID 38938274, 2024). "The FGFR2 IIIb splice isoform was more common in oestrogen-receptor-positive cancer, while the FGFR2 IIIc splice isoform was more common in HER2-positive carcinomas." (PMID 39596875, 2024). "Conversely, EM cells as well as FGFR2‐WT EC cells formed only a few colonies even in the presence of FGF7, suggesting that other factors drive anchorage‐independent cell growth in these cancer cells." (PMID 37165578, 2023). "The distribution of FGFR3 fusion differed from that of FGFR1 and FGFR2 fusions, indicating that the distribution of FGFR fusion genes is cancer type‐dependent." (PMID 37537783, 2023). "We sought to survey FGFR2 genetic alterations in ICC and pan-cancers using fluorescence in situ hybridization and next-generation sequencing." (PMID 37964396, 2023). "Another limitation of this study was a sample size of 31 enrolled patients as compared with 107 patients with FGFR2 rearrangements included in FIGHT‐202,26 because patient accrual in a single country usually takes a long time for rare cancers." (PMID 36127767, 2023). "Besides the numerous FGFR alterations in adult cancers, some alterations are strongly associated with pediatric low grade neuroepithelial lesions such as FGFR1 duplication, and FGFR1/3-TACC1 or FGFR2-CTNNA3 fusions may be considered as hallmarks of these tumors." (PMID 36495366, 2023). "This inhibitor differs from earlier TKIs with FGFR‒targeted activity due to its high selectivity for FGFR1, FGFR2, and FGFR3, making this inhibitor particularly attractive for the treatment of FGFR-driven cancers." (PMID 37715207, 2023). "A recent pan-cancer next-generation sequencing profiling demonstrated that ~7% of cancers harbor gain-of-function FGFR aberrations, with varying frequencies between family members (FGFR1 > FGFR3 > FGFR2 > FGFR4)." (PMID 36839989, 2023). "The docking analysis looked at the binding affinities of the compounds identified in GC–MS against cervical and oral cancer receptors such as ER, GCR, PR, HER2, VEGF, and FGFR2." (PMID 37598190, 2023). "The greatest functional evidence supporting this mechanism of activation comes from adult cancers, including FGFR1-amplified lung cancer and FGFR1- and FGFR2-amplified breast cancer." (PMID 37130917, 2023). "Similar effectiveness was observed by combining 227Th-targeted with an anti-fibroblast growth factor receptor 2 (FGFR2-TTC) and ATRi, leading to increased levels of γH2AX and cell cycle arrest compared to using either treatment alone in various cancer cells." (PMID 38140100, 2023). "To determine the clinical relevance of FGFR2 and FGF7 in RMS patient tumors, we analyzed gene expression data generated in the ITCC/CIT (Innovative Therapies for Children with Cancer/Carte d’Identite’ des Tumeurs) cohort." (PMID 34850536, 2022). "We have identified that multiple RTKs, such as EGFR, FGFR2, EPHA2, and MET, are key targets for C1GALT1 and their appropriate O-glycosylation is essential for cancer progression and metastasis." (PMID 35169131, 2022). "By specifically binding to IgIII of FGFR2, alofanib is able to inhibit the FGF2-induced phosphorylation of FRS2α with nanomolar activity in cancer cells expressing different FGFR2 isoforms." (PMID 35494629, 2022). "Fibroblast growth factor receptor 2 (FGFR2) and human epidermal growth factor receptor 2 (HER2) proteins are well-known molecular targets for cancer therapy." (PMID 35585358, 2022). "Gene alterations in the FGFR family (FGFR1, FGFR2, FGFR3, and FGFR4) have been reported in various cancers." (PMID 35954414, 2022).
cancer (continued). "Fibroblast growth factor receptor 2 (FGFR2) and human epidermal growth factor receptor 2 (HER2) proteins are both molecular targets for cancer therapy." (PMID 35585358, 2022). "Consistent with the literature, the results of the present study showed fusion of the FGFR2 gene with nine different partners, namely, TACC2, BICC1, BTBD16, WAC, HFM1, HOOK1, INPP5F, C10orf90, and WDR11, in five different types of cancer." (PMID 35342406, 2022). "Fibroblast growth factor receptor 2 (FGFR2) is a member of the FGFR family and is remarkably involved in human cancer pathogenesis." (PMID 35311468, 2022). "About 45% of the intrahepatic cholangiocarcinoma cases are coupled with FGFR2 fusion, half of which are with bicaudal C1 (BICC1); identification of FGFR2-BICC1 in other types of cancer is rare." (PMID 34207779, 2021). "Treatment of RTK-driven cancer cell lines with zotatifin for 24 h resulted in dose dependent downregulation of HER2, FGFR1 and FGFR2 protein levels, as well as cyclin D1 (a zotatifin target gene)." (PMID 34900714, 2021). "FGFR2 was the highest overexpressed kinase in both mRNA (mRNA overexpression rate, RNA = 21%) and protein (PRO = 23%) levels within a cancer cohort (UCEC), followed by FGFR1 (RNA = 18%, PRO = 23%, in LUAD)." (PMID 34552204, 2021). "Genetic aberrations of FGFR1 are more frequently observed in human cancers (2.86%), followed by alterations in FGFR3 (2.21%), FGFR2 (1.77%), and FGFR4 (1.54%)." (PMID 32962091, 2020). "Alterations in signaling in the FGF/FGFR2 pathway (e.g., overexpression of FGFR2 protein or amplification of FGFR2 gene) have been associated with GEA, breast, and other cancers and with a decreased prognosis, suggesting that inhibition of FGFR2 may be a rational target for cancer therapy." (PMID 32965540, 2020). "In EMT, ESRP1 was thought to directly regulate these subtypes such as FGFR2, ENAH, CD44 and CTNND, thereby losing cell-to-cell adhesion and polarity, increasing cancer cell invasion and migration." (PMID 32467669, 2020). "We have demonstrated that phosphorylation of multiple RTKs, such as EGFR, FGFR2, IGF1R, and MET, can be regulated by O-glycosylation in various cancers." (PMID 32005975, 2020). "As for the receptors of the FGF ligands, four distinct FGF receptors (FGFRs), FGFR1 (Flg), FGFR2 (K-sam), FGFR3, and FGFR4 exist, and if deregulated can function as oncogenes to drive specific cancer types including GC." (PMID 33178597, 2020). "The work presented here supports the evaluation of ABT263 or other Bcl‐XL inhibitors in combination with FGFR inhibition in other FGFR2‐ and FGFR3‐dependent cancers." (PMID 30537101, 2019). "3D185 inhibited FGFR1-, FGFR2-, FGFR3-, and CSF-1R-mediated cancer cell proliferation, with IC50 values ranging from 0.9 to 36.8 nM." (PMID 31438996, 2019). "Thus, ERK1/2-mediated phosphorylation of S780 in FGFR2 constitutes a negative feedback loop and inactivation of this feedback loop in cancer cells causes hyperactivation of FGFR2 signaling, which may result in increased invasive properties." (PMID 31146385, 2019). "Interestingly, a combination of an FGFR2 inhibitor and EGFR neutralizing antibody partially enhanced drug sensitivity of GC in vitro and in vivo, suggesting these RTKs may cause drug resistance in cancer cells under FGFR2 inhibition." (PMID 31242658, 2019). "Through enrichment analysis for the genes that undergo temporal changes in isoform expression in each cell line, we identified several pathways, which are related to cancer (SLIT/ROBO and FGFR2 signalling pathway)." (PMID 30857150, 2019). "To investigate how the downregulation of FGFR2 was relevant to cancer progression, we performed Gene Set Enrichment Analyses (GSEA) to identify gene sets related to the low expression of FGFR2." (PMID 30837551, 2019). "Taken together, these observations indicate that SCAT7/hnRNPK/YBX1 RNP plays a crucial role in the transcriptional activation of FGFR2 and/or FGFR3 in different cancer models." (PMID 29491376, 2018).